TRIM55 (tripartite motif containing 55)
Description:
E3 ubiquitin ligase that plays an important role in regulating cardiac development and contractility, muscle growth, metabolism, and fiber-type differentiation. Acts as a critical factor that regulates cardiomyocyte size during development in concert with TRIM63 by regulating E2F1-mediated gene expression (By similarity). Plays a role in apoptosis induction in cardiomyocytes by promoting ubiquitination of the DUSP1 phosphatase. Promotes non-canonical NF-kappa-B signaling and B-cell-mediated immune responses by mediating NFKB2 'Lys-48'-linked ubiquitination and processing. In turn, NFKB2 is further processed by valosin-containing protein/VCP, an ATPase that mediates ubiquitin-dependent protein degradation by the proteasome. May play a role in preventing macrophages from producing inflammatory factors and migrating by downregulating the level of nuclear NF-kappa-B subunit RELA. Also modifies PPARG via polyubiquitination and accelerates PPARG proteasomal degradation to inhibit its activity.
Synonyms: MuRF-2; MuRF2; RNF29
Tractability: No criterion of Open Targets' tractability assessment is met for any kind of drug.
Gene: Protein-coding gene on chromosome 8 (66,126,896 to 66,175,489, forward strand). Ensembl gene ENSG00000147573.
Subcellular location: Nucleus; Cytoplasm
Subcellular location (Human Protein Atlas): Golgi apparatus; Cytosol
Gene Ontology:
Molecular function: identical protein binding; protein binding; ubiquitin protein ligase activity; ubiquitin-like ligase-substrate adaptor activity; zinc ion binding
Biological process: positive regulation of non-canonical NF-kappaB signal transduction; protein K48-linked ubiquitination; innate immune response; signal transduction
Cellular component: cytoplasm; microtubule; nucleus
Genetic constraint (gnomAD): Loss-of-function variants: 49 observed, 60.9 expected, observed/expected ratio (o/e) 0.8, 90% interval 0.64 to 1.02. The upper end of that interval is the gene's LOEUF score, 1.02, which puts it in group 4 of 6, group 1 being the genes least tolerant of losing a copy. Missense variants: 670 observed, 688.37 expected, observed/expected ratio (o/e) 0.97, 90% interval 0.91 to 1.04. Synonymous variants: 232 observed, 246.49 expected, observed/expected ratio (o/e) 0.94, 90% interval 0.85 to 1.05.
Homologues: Orthologues: chimpanzee TRIM55 (99% identical), dog TRIM55 (93% identical), macaque TRIM55 (91% identical), pig TRIM55 (89% identical), guinea pig TRIM55 (89% identical), rabbit TRIM55 (86% identical), mouse Trim55 (85% identical), rat Trim55 (84% identical), tropical clawed frog trim55 (64% identical), zebrafish trim55a (44% identical), zebrafish trim55b (42% identical). Paralogues in human: TRIM54 (40% identical), TRIM63 (38% identical), MID1 (16% identical), MID2 (15% identical), TRIM36 (14% identical), TRIM58 (14% identical), TRIM38 (14% identical), TRIM46 (13% identical), TRIM11 (13% identical), TRIM22 (13% identical), TRIM42 (13% identical), TRIM7 (13% identical), and 68 more.
Diseases named in the same sentence as TRIM55 in open-access papers:
TRIM55 is named in the same sentence as 21 diseases in open-access papers, as found by Europe PMC text mining. Sharing a sentence is not in itself a finding about the gene and the disease. The quoted sentences say what the papers report.
cardiac hypertrophy (2 papers, 2020 to 2023). "TRIM55, which is a putative downstream target gene of miR-378a-3p, was also associated with normal cardiac function and physiological cardiac hypertrophy." (PMID 32463795, 2020). "In this study, following finding luteolin prevents cardiac hypertrophy and heart failure via activating PPARγ pathway, and we also found that by binding to PPARγ luteolin interrupted the interaction between TRIM55 and PPARγ and prevents the TRIM55-mediated proteasome-dependent degradation of PPARγ." (PMID 36998980, 2023). "However, although TRIM55 is sufficient for normal cardiac function and simultaneous absence of TRIM55 and TRIM63 results in physiological cardiac hypertrophy, its role in myocardial I/R injury is still not elucidated." (PMID 32463795, 2020).
colorectal cancer (2 papers, 2023 to 2024). A primary or metastatic malignant neoplasm that affects the colon or rectum. "In colorectal cancer, TRIM55 targets c-Myc and downregulates its protein level via ubiquitination, thereby suppressing tumor growth." (PMID 39420007, 2024). "In colorectal cancer, TRIM55 induces the degradation of oncoprotein c-Myc to suppress growth and metastasis." (PMID 39420007, 2024).
hepatocellular carcinoma (2 papers, 2022 to 2024). A malignant tumor that arises from hepatocytes. "The forced expression of TRIM55 inhibits hepatocellular carcinoma cell migration and invasion by reversing the epithelial to mesenchymal transition." (PMID 35371994, 2022).
lung adenocarcinoma (2 papers, 2022 to 2024). A carcinoma that arises from the lung and is characterized by the presence of malignant glandular epithelial cells. "For example, downregulation of TRIM55 is closely associated with chemo-resistance, migration, and cancer stem-cell-like phenotype of lung adenocarcinoma cells via regulation of Snail1 degradation." (PMID 39420007, 2024). "Snail1, the pivotal transcriptional regulator of EMT process, has been identified as a substrate of TRIM55 in lung adenocarcinoma cells." (PMID 39420007, 2024). "By augmenting protein degradation of Snail1 via promoting the ubiquitination pathway, TRIM55 inhibits the malignant behavior of lung adenocarcinoma." (PMID 36419120, 2022).
Cirrhosis (1 paper, 2024). A chronic disorder of the liver in which liver tissue becomes scarred and is partially replaced by regenerative nodules and fibrotic tissue resulting in loss of liver function. "However, no conspicuous correlation was observed between TRIM55 expression and other factors, including age, gender, differentiation grade, satellite lesion, vascular thrombus, serum HBV level, cirrhosis, and metastasis." (PMID 39420007, 2024).
diabetic cardiomyopathy (1 paper, 2020). Diabetic cardiomyopathy is a disorder of the heart muscle in people with diabetes. "TRIM55 was also identified as the first ubiquitin ligase to inhibit PPAR expression via post-translational ubiquitination and to protect against diabetic cardiomyopathy." (PMID 32463795, 2020).
dilated cardiomyopathy (1 paper, 2021). Cardiomyopathy which is characterized by dilation and contractile dysfunction of the left and right ventricles. "Moreover, it was found that miR-378a-3p might exert a cardioprotective effect against ischemic heart disease targeting Tripartite Motif 55 (TRIM55), which is involved in dilated cardiomyopathy, cardiomyocyte apoptosis, and differentiation." (PMID 33573156, 2021).
liver cancer (1 paper, 2022). An epithelial or non-epithelial malignant neoplasm that arises from the liver. "We predicted that the patients with liver cancer with high TRIM11 and TRIM55 mRNA expression would have high OS (p = 0.0031 and 0.0044, respectively) and DSS (p = 0.0045 and 0.033, respectively)." (PMID 35142083, 2022).
SARS-CoV infection (1 paper, 2015). "We narrowed one locus to a single candidate gene, Trim55, and confirmed its role in the inflammatory response to SARS-CoV infection through the use of knockout mice." (PMID 26452100, 2015). "Our data demonstrate that Trim55 contributes to vascular cuffing following SARS-CoV infection." (PMID 26452100, 2015).
cancer (3 papers, 2019 to 2025). A tumor composed of atypical neoplastic, often pleomorphic cells that invade other tissues. "TRIM55, a muscle-specific E3 ubiquitin ligase, plays a critical role in sarcomere organization and myofiber maintenance, and its expression has been linked to tumor differentiation and prognosis across cancers, supporting the retained myogenic features of ERMS." (PMID 40710368, 2025). "The previous studies using PLATO have identified a set of TRIM proteins (TRIM1/MID2, TRIM18/MID1, TRIM54 and TRIM55) as cancer autoantigens of paraneoplastic neurological disorder (PND)." (PMID 31494268, 2019).
tumor (3 papers, 2023 to 2025). "The diminished levels of TRIM55 were significantly associated with larger tumor size and elevated serum AFP levels." (PMID 39420007, 2024). "Intriguingly, we discovered a significant association between reduced TRIM55 expression and larger tumor size (p = 0.008) as well as elevated serum alpha-fetoprotein (AFP) levels (p = 0.026)." (PMID 39420007, 2024). "Collectively, our findings underscore the significance of NF90 in the tumor-suppressive role of TRIM55 in HCC." (PMID 39420007, 2024). "Given that angiogenesis serves as the foundation for tumor growth, invasion, and metastasis, we sought to explore the functional significance of TRIM55 in the regulation of HCC angiogenesis." (PMID 39420007, 2024). "Taken together, our results indicate that the enforced expression of HIF1α and TGF-β2 can counterbalance the tumor-suppressive impact of TRIM55 in HCC." (PMID 39420007, 2024). "Furthermore, analysis of the TCGA database confirmed a negative correlation between TRIM55 expression and VEGF levels in tumor tissues, thereby providing additional support for TRIM55’s regulation of VEGF." (PMID 39420007, 2024). "Moreover, both tumor weight and volume were significantly lower in the TRIM55 overexpression group than in the control group." (PMID 39420007, 2024). "Moreover, the Kaplan–Meier survival analysis revealed that HCC patients with low TRIM55 expression experienced significantly shorter overall and tumor-free survival times compared to those with high TRIM55 expression." (PMID 39420007, 2024). "Since HIF1α plays a critical role in tumor angiogenesis, we also examined whether the anti-angiogenesis role of TRIM55 is dependent on HIF1α." (PMID 39420007, 2024). "Furthermore, we unveiled a novel role of TRIM55 in impeding tumor angiogenesis." (PMID 39420007, 2024). "The downregulation of TRIM55 expression correlated with larger tumor size and elevated serum alpha-fetoprotein (AFP), and predicted unfavorable overall and tumor-free survival." (PMID 39420007, 2024). "TRIM55 exerted inhibitory effects on the proliferation, migration, and invasion of HCC cells in vitro, and effectively suppressed tumor growth in vivo." (PMID 39420007, 2024). "Moreover, overexpression of TRIM55 could suppress CRC cell growth in vitro and inhibit CRC xenograft tumor development in vivo." (PMID 37212463, 2023).
infection (1 paper, 2015). The state of being infected such as from the introduction of a foreign agent such as serum, vaccine, antigenic substance or organism. "Higher expression of Claudin19 at day two post infection in Trim55 deficient mice likely contributes to decreased tight junction permeability and reduced ability for inflammatory cells in the bloodstream to cross the endothelial barrier." (PMID 26452100, 2015). "RNA was isolated from the lungs of mock and infected control and Trim55-/- mice at two and days four post infection." (PMID 26452100, 2015). "Within the HrS1 QTL, a combination of approaches applied to the CC platform predicted a single gene candidate, Trim55, as the principle regulator of vascular cuffing after infection." (PMID 26452100, 2015). "Increased expression of Ccl24, CCR3, IL4 and Pdgfc in C57BL/6J mice compared to that in Trim55-/- mice at day four post infection correlates with increased inflammatory cell recruitment and binding to extracellular matrix proteins." (PMID 26452100, 2015).
infectious disease (1 paper, 2015). A disorder directly resulting from the presence and activity of a microbial, viral, or parasitic agent in humans. "We focused our validation efforts on Trim55, the single HrS1 candidate and a member of the TRIM protein superfamily which has not previously been associated with any infectious disease phenotype." (PMID 26452100, 2015).
myopathy (1 paper, 2021). A disease of the muscle in which the muscle fibers do not function properly. "Likewise, the combined germ line deletion of Trim63/MuRF1 and Trim54/MuRF3 as well as the deletion of Trim55/MuRF2 and Trim54/MuRF3 caused a myosin storage myopathy of the heart and skeletal muscle in mice." (PMID 34572540, 2021).
TRIM55 also shares sentences with these, for which no sentence is quoted: attention deficit-hyperactivity disorder (1 paper); heart failure (1); ischemic heart disease (1); liver disease (1); lung carcinoma (1); schizophrenia (1); X-linked intellectual disability (1).